TRGJP (T cell receptor gamma joining P)
Synonyms: JP; TCRGJP
Gene: T-cell receptor joining (J) gene on chromosome 7 (38,273,587 to 38,273,647, reverse strand). Ensembl gene ENSG00000211691.
Genetic constraint (gnomAD): Missense variants: 27 observed, 24.54 expected, observed/expected ratio (o/e) 1.1, 90% interval 0.81 to 1.52. Synonymous variants: 11 observed, 9.46 expected, observed/expected ratio (o/e) 1.16, 90% interval 0.73 to 1.8.